GOSR2 (golgi SNAP receptor complex member 2)
Description:
Involved in transport of proteins from the cis/medial-Golgi to the trans-Golgi network.
Synonyms: GS27; Bos1; EPM6; MYOS
Tractability: Antibody: UniProt predicts a signal peptide or a membrane-spanning region. PROTAC: ubiquitination databases record sites on it; its protein half-life has been measured.
Gene: Protein-coding gene on chromosome 17 (46,923,075 to 46,975,524, forward strand). Ensembl gene ENSG00000108433.
Subcellular location: Golgi apparatus, cis-Golgi network membrane; Golgi apparatus membrane; Endoplasmic reticulum membrane
Subcellular location (Human Protein Atlas): Golgi apparatus; Nucleoplasm
Pathways (Reactome):
Vesicle-mediated transport: COPI-mediated anterograde transport; COPII-mediated vesicle transport; Cargo concentration in the ER; Intra-Golgi traffic
Cellular responses to stimuli: XBP1(S) activates chaperone genes
Gene Ontology:
Molecular function: protein binding; SNAP receptor activity; SNARE binding
Biological process: endoplasmic reticulum to Golgi vesicle-mediated transport; intra-Golgi vesicle-mediated transport; membrane fusion; vesicle-mediated transport
Cellular component: Golgi apparatus; Golgi membrane; membrane; endoplasmic reticulum membrane; endoplasmic reticulum-Golgi intermediate compartment membrane; ER to Golgi transport vesicle membrane; late endosome membrane; SNARE complex; cytoplasm; endomembrane system
Genetic constraint (gnomAD): Loss-of-function variants: 13 observed, 16.26 expected, observed/expected ratio (o/e) 0.8, 90% interval 0.52 to 1.27. The upper end of that interval is the gene's LOEUF score, 1.27, which puts it in group 5 of 6, group 1 being the genes least tolerant of losing a copy. Missense variants: 165 observed, 173.28 expected, observed/expected ratio (o/e) 0.95, 90% interval 0.84 to 1.08. Synonymous variants: 58 observed, 66.29 expected, observed/expected ratio (o/e) 0.87, 90% interval 0.71 to 1.09.
Gene-disease validity (ClinGen):
ClinGen rates the evidence that GOSR2 causes each of these diseases.
progressive myoclonus epilepsy (autosomal recessive): Definitive. A rare group of disorders characterized by the development of myoclonic and tonic-clonic epileptic seizures associated with progressive degeneration of the nervous system.
Homologues: Orthologues: rabbit GOSR2 (92% identical), chimpanzee GOSR2 (92% identical), rat Gosr2 (91% identical), dog GOSR2 (90% identical), guinea pig GOSR2 (89% identical), mouse Gosr2 (88% identical), chimpanzee GOSR2 (87% identical), macaque GOSR2 (84% identical), pig GOSR2 (81% identical), zebrafish gosr2 (75% identical). Paralogues in human: VTI1A (19% identical), VTI1B (18% identical).
Diseases named in the same sentence as GOSR2 in open-access papers:
GOSR2 is named in the same sentence as 37 diseases in open-access papers, as found by Europe PMC text mining. Sharing a sentence is not in itself a finding about the gene and the disease. The quoted sentences say what the papers report.
progressive myoclonus epilepsy (9 papers, 2017 to 2025). "Gosr2 gene was identified as a causative gene for progressive myoclonus epilepsy with distinct clinical features include scoliosis." (PMID 37752218, 2023). "Biallelic variants in the Golgi SNAP receptor complex member 2 gene (GOSR2) have been reported in progressive myoclonus epilepsy with neurodegeneration." (PMID 37895210, 2023). "Pathogenic variants in GOSR2 were first described to cause progressive myoclonus epilepsy and ataxia with rare concomitant manifestation of CMD." (PMID 34779586, 2021). "North Sea Progressive Myoclonus Epilepsy is a rare and severe disorder caused by mutations in the GOSR2 gene." (PMID 28264719, 2017). "Mutations in GOSR2 are associated with progressive myoclonus epilepsies (PMEs), characterized by myoclonus, generalized tonic clonic seizures, and ataxia." (PMID 28982678, 2017). "It is a single orthologue of the human Golgi SNAP receptor complex member 2 (GOSR2) that is associated with progressive myoclonic epilepsy (PME), a severe epilepsy syndrome characterized by childhood-onset myoclonus, ataxia, seizures and subsequent neurological decline." (PMID 32899411, 2020). "North Sea‐Progressive Myoclonus Epilepsy (NS‐PME) is a childhood‐onset neurological disorder caused by mutations in the GOSR2 gene." (PMID 41261947, 2025). "Biallelic variants in the Golgi SNAP receptor complex member 2 gene (GOSR2) have been reported in progressive myoclonus epilepsy (PME, OMIM#614018)." (PMID 37895210, 2023). "North Sea‐Progressive Myoclonus Epilepsy (NS‐PME) is a progressive neurological disorder, initially only associated with the homozygous GOSR2 founder mutation (c.430G>T; p.Gly144Trp)." (PMID 41261947, 2025). "GOSR2 encodes a Golgi SNARE protein involved in vesicle trafficking, with variants linked to progressive myoclonus epilepsy and cardiovascular disease risk." (PMID 41172738, 2025).
Ataxia (5 papers, 2019 to 2025). Ataxia refers to impaired coordination of voluntary muscle movement. "The classic phenotype associated with mutations in GOSR2 typically includes early‐onset ataxia, progressive myoclonic jerks and epilepsy." (PMID 41261947, 2025). "Note that missense mutations in GOSR2 lead to a neurological phenotype of progressive epilepsy and ataxia." (PMID 37199746, 2023). "In humans, double Gly144Trp mutants in GOSR2 had progressive cortical myoclonus and ataxia with areflexia, showing reduced motor unit recruitment given chronic partial denervation." (PMID 30791866, 2019).
epilepsy (5 papers, 2017 to 2025). A brain disorder characterized by episodes of abnormally increased neuronal discharge resulting in transient episodes of sensory or motor neurological dysfunction, or psychic dysfunction. "GOSR2 mutations lead to progressive neurological disorders, primarily characterized by myoclonus ataxia/epilepsy, muscular dystrophy, and hearing loss." (PMID 41261947, 2025). "These patients not only expand the mutational and phenotypic spectrum of North Sea PME but also suggest that GOSR2 should be added to the list of monogenic causes of dystonia, epilepsy, and global delay." (PMID 38397161, 2024).
Hypertension (5 papers, 2020 to 2024). The presence of chronic increased pressure in the systemic arterial system. "The hypertension-associated m6A-SNP (Lys67Arg) in the GOSR2 gene is the same as previously associated with the disease." (PMID 35991314, 2022). "Two of the recurrent AF genes also code for functions directly or indirectly linked to AF (CASQ2 and GOSR2), and some genes indicate a possible indirect link related to comorbidities, e.g., hypertension or malignancy (PPFIA4, USP34, WIPF1, SPATS2L, CAND2, and AOPEP)." (PMID 38725839, 2024). "For PC1, shared genetic variants with diastolic blood pressure (ATXN2, GOSR2, NOS3, BAG3) and hypertension (ATXN2, VEGFB, NOS3, BAG3) were also observed." (PMID 39543113, 2024).
congenital muscular dystrophy (4 papers, 2018 to 2025). A muscular dystrophy that is characterized by diminished muscle tone (hypotonia), progressive muscle weakness and degeneration (atrophy), abnormally fixed joints, spinal rigidity, and delays in reaching motor milestones such as sitting or standing unassisted. "Recessive mutations in TRAPPC11 and GOSR2 are associated with congenital muscular dystrophy and hypoglycosylation of α-dystroglycan." (PMID 29855340, 2018). "Another phenotype of mutations in GOSR2 is congenital muscular dystrophy (CMD)." (PMID 41261947, 2025). "While mutations in GOSR2 were initially linked primarily to PMA/PME, they should also be considered in persons with hearing loss, congenital muscular dystrophy (CMD), or a combination of these phenotypes." (PMID 41261947, 2025).
muscular dystrophy (4 papers, 2018 to 2025). Muscular dystrophy (MD) refers to a group of more than 30 genetic diseases characterized by progressive weakness and degeneration of the skeletal muscles that control movement. "Biallelic variants in GOSR2 are a known cause for neurodevelopmental disorders clinically manifesting with epilepsy, scoliosis, and congenital myasthenic syndromes with rare cases of concomitant muscular dystrophy reported." (PMID 34779586, 2021). "Congenital muscular dystrophies are emerging as a rare clinical manifestation of IDT and have only recently been reported in individuals with progressive muscle weakness and seizures, whom were found to have recessive variants in TRAPPC11 and in rare patients with GOSR2 variants." (PMID 34779586, 2021).
epilepsy syndrome (3 papers, 2017 to 2021). A syndrome that has a characteristic cluster of clinical features and/or lectroencephalographic (EEG) findings that reflect underlying epileptic activity. "Finally, given that GOSR2-PME is an epilepsy syndrome, we tested whether such neuronal hyperactivity and the dendritic/synaptic morphological abnormalities resulted in seizure-like neuronal activity." (PMID 28978487, 2017).
coronary artery disease (2 papers, 2017 to 2022). "The aim of the present study is to assess the association between the human GOSR2 gene and coronary artery disease using a haplotype-based case-control study in Chinese Han population." (PMID 29137253, 2017). "The data indicates that in Chinese Han population, the G-T haplotype established by rs3785889-rs16941382 of the human GOSR2 gene might be the risk marker for coronary artery disease." (PMID 29137253, 2017). "Then the association between GOSR2 and coronary artery disease may be established via miRNA-4513 pathway." (PMID 29137253, 2017). "A total of 283 coronary artery disease patients and 280 controls were genotyped for the human GOSR2 gene (rs197932, rs3785889, rs197922, rs17608766, and rs16941382)." (PMID 29137253, 2017).
developmental delay (2 papers, 2021 to 2023). "The first patient, a male compound heterozygous for the GOSR2 splice site variant c.336+1G>A and the novel c.364G>A,p.Glu122Lys missense variant showed global developmental delay and seizures at the age of 2 years, followed by myoclonus at the age of 8 years with partial response to clonazepam." (PMID 37895210, 2023). "However, dysfunctions in STX1B and GOSR2 are less commonly associated with developmental delay, as most of the affected individuals don't show intellectual impairment." (PMID 35095745, 2021).
Dystonia (2 papers, 2023 to 2024). An abnormally increased muscular tone that causes fixed abnormal postures. "Moreover, this study introduces the possibility that patients with isolated dystonia may be heterozygous for GOSR2 variants." (PMID 38397161, 2024). "The presentation with juvenile-onset dystonia suggests that GOSR2 may also be included in the differential diagnoses of monogenetic dystonia." (PMID 37895210, 2023).
myocardial infarction (2 papers, 2017 to 2019). Gross necrosis of the myocardium, as a result of interruption of the blood supply to the area, as in coronary thrombosis. "One study based on American population reported that the A allele in rs197922 of GOSR2 gene was a risk factor for myocardial infarction (OR=1.17, P=0.032)." (PMID 29137253, 2017). "One study based on American population reported that the A allele in rs197922 of GOSR2 gene was a risk factor for myocardial infarction (MI) (OR=1.17, P=0.032)." (PMID 29137253, 2017). "GOSR2 is associated with hypertension, CAD and myocardial infarction (MI)." (PMID 31775219, 2019).
arteriosclerosis (1 paper, 2017). A vascular disorder characterized by thickening and hardening of the walls of the arteries. "The association with blood pressure may accelerate the arteriosclerosis which would consequently make the some haplotypes in GOSR2 gene the risk factor of CAD." (PMID 29137253, 2017).
breast carcinoma (1 paper, 2024). "Comparative analysis with the well-established MCF-10A reference cell line revealed a significant upregulation of APOA5, CHAC1, EMID1, GOSR2, TCP1, and TMEM167A in breast cancer cell lines." (PMID 38300336, 2024).
disorder of glycosylation (1 paper, 2025). A disease that has its basis in the disruption of glycosylation. "Studying fibroblasts and muscle cells from persons with NS‐PME to determine the presence of glycosylation defects could provide crucial insights into the disease mechanisms and potentially redefine GOSR2‐associated disorders as part of the Congenital Disorders of Glycosylation (CDG) spectrum." (PMID 41261947, 2025).
metabolic syndrome (1 paper, 2022). A cluster of metabolic risk factors for CARDIOVASCULAR DISEASES and TYPE 2 DIABETES MELLITUS. "Examples of validated variants within microRNAs included in this catalog are miR-196a2 variant rs11614913 regulating SFMBT1 and HOXC8 in metabolic syndrome, and miR-4513 variant rs2168518 regulating GOSR2 in cardiometabolic diseases." (PMID 35365203, 2022).
Parkinson disease (1 paper, 2019). A progressive degenerative disorder of the central nervous system characterized by loss of dopamine producing neurons in the substantia nigra and the presence of Lewy bodies in the substantia nigra and locus coeruleus. "Stx5 may also play a role in Parkinson’s disease, as a disease-related mutant of α-synuclein (A53T) binds to Stx5 and GosR2, and this reduces the formation of the Stx5-GosR2-Bet1-Sec22b SNARE complex, thereby possibly impairing ER-Golgi transport." (PMID 31357511, 2019).
viral infections (1 paper, 2023). "Future studies may address how viral infection potentially adds on to disorders in COPII-related trafficking or autophagosome biogenesis on the background of biallelic GOSR2 deficiency." (PMID 37895210, 2023).
cardiovascular disease (2 papers, 2017 to 2025). "Due to its trafficking function, the GOSR2 gene could be associated with the cardiovascular diseases which are highly associated with macromolecules such as insulin, leptin, and angiotensinogen." (PMID 29137253, 2017).
bacterial infections (1 paper, 2023). "Further work is needed to elucidate the role of viral and bacterial infections in the disease progression in patients with GOSR2 deficiency and how pathogen-induced perturbation of vesicular trafficking may eventually trigger neurodegeneration." (PMID 37895210, 2023).
cancer (1 paper, 2022). A tumor composed of atypical neoplastic, often pleomorphic cells that invade other tissues. "All other coding genes LPHN2, EFNA1, ISL1, TRIM29, PAWR, and GOSR2 were differentially up- or downregulated in different cancers." (PMID 36352089, 2022).
tumor (1 paper, 2021). "Interestingly DDIT3 co‐expression with GOSR2 (protein transport) and ASNS (asparagine synthetase) remained coordinated, suggesting that some less known aspects of DDIT3 activity may benefit tumor cells." (PMID 34698427, 2021).
GOSR2 also shares sentences with these, for which no sentence is quoted: movement disorder (2 papers); atherosclerosis (1); cataract (1); congenital heart disease (1); Dravet syndrome (1); essential hypertension (1); genetic disorders (1); hearing loss (1); intellectual impairment (1); juvenile-onset dystonia (1); myoclonic seizures (1); neurological disorder (1); osteoarthritis (1); Progressive myoclonic epilepsy (1); progressive myoclonus ataxia (1); progressive myoclonus epilepsy type 6 (1).